FABP1 (fatty acid binding protein 1)
Diseases named in the same sentence as FABP1 in open-access papers (continued):
Sharing a sentence is not in itself a finding about the gene and the disease.
liver cirrhosis (3 papers, 2019 to 2025). "Additionally, another six genes (ALB, APOH, FABP1, FGB, FGG, and TF) were identified from our previous HCC EV-specific gene panel given their performance in distinguishing early-stage HCC from liver cirrhosis." (PMID 40307890, 2025).
prostate carcinoma (3 papers, 2004 to 2021). A carcinoma that arises from epithelial cells of the prostate gland. "Analysis of biological processes revealed that the FABP1 gene had significant involvement in “recurrent gene fusions in prostate cancer”, “transcription_FXR-regulated cholesterol and bile-acid cellular transport”, and “transcription_HIF-1 targets” in CRC development." (PMID 34680577, 2021).
viral hepatitis (3 papers, 2022 to 2024). An acute or chronic inflammation of the liver parenchyma caused by viruses. "Network 2 contained 430 DMRs and was observed in viral hepatitis and HCC populations with three potential hub genes (FABP1, SGK2, and HNF4A)." (PMID 38302914, 2024). "Network 2 was observed in viral hepatitis and HCC, with three potential hub genes: fatty acid binding protein 1 (FABP1), serum/glucocorticoid regulated kinase 2 (SGK2), and hepatocyte nuclear factor 4 α (HNF4A)." (PMID 38302914, 2024). "Increased methylation levels of the FABP1 gene may be correlated with reduced protection of hepatocytes from oxidative metabolites in NAFLD and viral hepatitis." (PMID 35655171, 2022).
adenocarcinomas of the lung (2 papers, 2015 to 2022). "As FABP1 expression was virtually absent in adenocarcinomas of the lung, FABP1 immunohistochemistry might be particularly helpful to assist in the identification of metastatic colorectal or gastrointestinal adenocarcinoma to the lung." (PMID 35951102, 2022). "As FABP1 expression is virtually absent in adenocarcinomas of the lung, FABP1 immunohistochemistry might be most helpful for its distinction from metastatic adenocarcinoma to the lung." (PMID 35951102, 2022).
ductal adenocarcinoma (2 papers, 2022 to 2023). "Moreover, in case of an adenocarcinoma in the pancreas, FABP1 positivity would argue in favor of a carcinoma derived from the ampulla of Vater (23% positive) and against a ductal adenocarcinoma (1.8% positive)." (PMID 35951102, 2022).
E. coli infection (2 papers, 2018 to 2025). "A number of genes involved in fatty acid transport, such as fatty acid-binding protein 1 (Fabp1) and four apolipoproteins (Apoa1, 2, 5 and Apoc3), were downregulated by E. coli infection in Mkp-1+/+ mice." (PMID 30563203, 2018).
fibrosis (2 papers, 2020 to 2025). the formation of excess fibrous connective tissue in an organ or tissue in a reparative or reactive process. "Moreover, the levels of macrophage chemotactic and activating factors such as MCP-1 and MCP-3 were significantly suppressed by the expression of renal FABP1, as well as the expressions of TGF-β and α1COL I, which are associated with fibrosis." (PMID 32038102, 2020).
kidney cancer (2 papers, 2022 to 2023). Primary or metastatic malignant neoplasm involving the kidney. "With respect to molecular mechanisms for FABP1 inactivation, it is also remarkable that FABP1 expression is virtually absent in kidney cancers, although the protein is abundantly seen in the normal kidney." (PMID 35951102, 2022).
liver failure (2 papers, 2014 to 2019). A liver disease characterized by the liver losing or has lost all of its function. "The protective effect of FABP1 in AAP induced liver failure was assessed by detecting cellular LDH release." (PMID 24606952, 2014).
malaria (2 papers, 2022 to 2023). Malaria is a serious and sometimes fatal disease caused by a parasite that commonly infects a certain type of mosquito which feeds on humans. "Six genes (TGFB1, CD36, THBS1, FABP1, PCK1, and IRS1) were involved with malaria, PPAR signaling, and the adipocytokine signaling pathway." (PMID 36193307, 2022). "Among them, malaria, PPAR signaling, and the adipocytokine signaling pathway reached statistical significance (FDR value of <1 and p < 0.05) and included TGFB1, CD36, THBS1, FABP1, PCK1, and IRS1." (PMID 36193307, 2022).
nasal polyps (2 papers, 2011 to 2022). "In addition, it is unknown whether the elevation in FABP1 is the cause of aspirin hypersensitivity or the result of extensive inflammation in the nasal polyps of patients with AERD." (PMID 21829647, 2011). "Our immunohistochemical results indicate that FABP1 is expressed more abundantly in the nasal polyps of AERD patients." (PMID 21829647, 2011). "FABP1-expression based on immunoblotting and immunohistochemical analysis was significantly higher in the nasal polyps of patients with AERD compared to that in patients with ATA." (PMID 21829647, 2011). "Of note, our immunohistochemical results demonstrate that FABP1 is significantly elevated in the nasal polyps of AERD patients compared to ATA patients." (PMID 21829647, 2011). "Among them, FABP1 levels were significantly higher in the nasal polyps of the AERD patients compared to the ATA patients based on our Western blot results." (PMID 21829647, 2011). "Immunohistochemical staining showed markedly increased expression of FABP1 in the nasal polyps of the AERD patients compared to those with ATA." (PMID 21829647, 2011). "Western blotting and immunohistochemical staining were performed to compare the amount of fatty acid-binding protein 1 (FABP1) in the nasal polyps of patients with AERD and ATA." (PMID 21829647, 2011). "This indicates that an increase in FABP1 abundance in nasal polyps may be related to the development of AERD and may be a useful marker for diagnostic and therapeutic trials." (PMID 21829647, 2011). "To investigate whether FABP1 expression was altered in nasal polyps, we performed Western blotting and immunohistochemical staining using nasal polyps obtained from similar subjects with ATA (n = 5) and AERD (n = 8)." (PMID 21829647, 2011). "The reason for the increase in FABP1 in the nasal polyps of the AERD patients is unknown." (PMID 21829647, 2011). "Fatty acid-binding protein 1 (FABP1) expression in immunoblotting and immunohistochemical analysis was significantly higher in nasal polyps from AERD patients." (PMID 35628512, 2022). "Immunohistochemical staining of serial sections for FABP1, SMA, CD163, and MBP was performed on 4-μm sections of paraffinized nasal polyp samples." (PMID 21829647, 2011).
psoriasis (2 papers, 2022). An autoimmune condition characterized by red, well-delineated plaques with silvery scales that are usually on the extensor surfaces and scalp. "Moreover, considering the current perception of psoriasis as a kind of systemic inflammatory condition, FABP-1 could become an indicator of systemic inflammation in such patients." (PMID 36144237, 2022). "FABP-1 and FABP-5 may become potential markers of metabolic complications and inflammation in psoriasis." (PMID 36144237, 2022).
Stroke (2 papers, 2023). Sudden impairment of blood flow to a part of the brain due to occlusion or rupture of an artery to the brain. "Hence, in clinical diagnosis and treatment, serum marker tests for A2M, LBP, CTSG, CST3, and FABP1 should be prioritized in patients with a high suspicion of stroke for early detection and timely intervention." (PMID 38090270, 2023). "Although FABP1 Thr94Ala polymorphisms are also likely related to influence plasma lipid levels, we found that blood lipid levels were not related to stroke risk under all genotype models." (PMID 37091779, 2023).
Abdominal obesity (1 paper, 2023). Excessive fat around the stomach and abdomen. "FABP1’s correlation extends further, aligning with glycemia, HbA1c levels, and abdominal obesity delineated through WTH ratios." (PMID 37792298, 2023).
adenosquamous carcinoma (1 paper, 2024). A carcinoma composed of malignant glandular cells and malignant squamous cells. "Interestingly, 35 out of 62 GBC expressed high levels of FABP1 in DI region, which include 28 out of 49 adenocarcinomas, 1 out of 5 neuroendocrine carcinomas, 2 out of 4 adenosquamous carcinomas, and all of 2 mixed adenoneuroendocrine carcinomas and 2 undifferentiated carcinomas." (PMID 38617005, 2024).
alcoholic hepatitis (1 paper, 2022). Acute hepatitis resulting from ingestion of alcohol. "Therefore, increased methylation levels of FABP1 could deteriorate the protection of hepatocytes from oxidative metabolites in NAFLD as well as in viral and alcoholic hepatitis, while decreased FABP1 methylation levels in HCC may be related to the promotion of cell growth." (PMID 35655171, 2022). "Common changes in the methylation levels of FABP1, SGK2, and HNF4A from fibrosis to cancer were found in NAFLD, hepatitis virus, and alcoholic hepatitis." (PMID 35655171, 2022). "The overall findings indicate that the formation of DMR networks involving FABP1, SGK2, and HNF4A could cooperatively and/or synergistically affect fibrosis and carcinogenesis in advanced NAFLD and viral and alcoholic hepatitis." (PMID 35655171, 2022).
bile reflux (1 paper, 2023). "Overall, the correlation network “DCA–Rikenellaceae RC9 gut group–RGD1311575/Fabp1” created a cancer-promoting microenvironment in the stomach during the development of bile reflux-related GIM." (PMID 37206332, 2023). "The DCA–Rikenellaceae RC9 gut group–RGD1311575/Fabp1 axis might be a key controller in the development of bile reflux-induced GIM." (PMID 37206332, 2023). "The DCA–Rikenellaceae RC9 gut group–RGD1311575/Fabp1 axis might play a key role in the mechanism of bile reflux-related GIM." (PMID 37206332, 2023). "Compared with the control group, the expressions of Fabp1 and Dgat1 in gastric antrum tissue of GIM rats induced by bile reflux were increased." (PMID 37206332, 2023).
brain injury (1 paper, 2025). Acute and chronic (see also brain INJURIES, CHRONIC) injuries to the brain, including the cerebral hemispheres, CEREBELLUM, and brain STEM. "Conversely, fatty acid-binding proteins (FABP1, FABP3, FABP4, FABP7) decreased over time in uninjured infants but increased in those with brain injury, suggesting a role in exacerbating damage." (PMID 40924950, 2025).
Cachexia (1 paper, 2020). Severe weight loss, wasting of muscle, loss of appetite, and general debility related to a chronic disease. "Also, expression of PEPCK, DGAT2, and FABP1 tended to be up‐regulated in cachexia." (PMID 33084249, 2020).
chronic pancreatitis (1 paper, 2011). A chronic inflammatory process causing damage and fibrosis of the pancreatic parenchyma. "A single study of gene array analysis in a cohort of 21 patients revealed FABP-1 overexpression (16x) in PaC compared to chronic pancreatitis and normal pancreatic tissue, though no further testing was performed to validate this association." (PMID 21251264, 2011).
colon adenocarcinoma (1 paper, 2021). "We also present in boxplot visualizations comparisons of the expressions of FABP genes in normal, colon adenocarcinoma (COAD), and rectal adenocarcinoma (READ) tissues, which showed that the FABP1, FABP4, and FABP6 genes had significantly different expression levels in normal and CRC tissues." (PMID 34680577, 2021).
cystic fibrosis (1 paper, 2025). Autosomal recessive disorder caused by pathogenic variants in the CFTR gene (cystic fibrosis transmembrane conductance regulator), which encodes a chloride and bicarbonate channel expressed in epithelial cells, and follow the diagnosis criteria. "This revealed an additional 67 significantly differentially expressed protein groups between cystic fibrosis patients and healthy individuals, including GUCA2A, ADAMDEC1, and FABP1 (upregulated) and GP2 (downregulated)." (PMID 40425748, 2025).
dystrophinopathy (1 paper, 2018). "Interestingly, the liver isoform FABP1 was shown not to be majorly affected in liver tissue in dystrophinopathy." (PMID 30386187, 2018).
fatty acid metabolism disorder (1 paper, 2014). "In analysis of RT-PCR, the low expression of Fabp1 in model group suggests that Fabp1 activity inhibiting may reduce stearic acid, glycocholate and hexadecanedioic acid, and lead to fatty acid metabolism disorder." (PMID 24454691, 2014).
hyperuricemia (1 paper, 2022). An abnormally high level of uric acid. "Preoperative FABP1 levels were risk factors for hyperuricemia at baseline." (PMID 36277716, 2022). "In this study, we also found that serum FABP1 levels were closely related to UA, liver enzyme and glucose metabolism parameters; moreover, it is worth highlighting that after adjusting for confounding factors, preoperative FABP1 level was a risk factor for hyperuricemia at baseline." (PMID 36277716, 2022). "In addition, serum FABP1 levels positively correlated with UA levels, and the preoperative serum FABP1 levels may be a risk factor for hyperuricemia." (PMID 36277716, 2022). "The current study applied a variety of statistical methods to elucidate the relationship between serum FABP1 levels and hyperuricemia before and after LSG for the first time." (PMID 36277716, 2022). "Our findings may provide a basis for encouraging researchers and clinicians working on metabolic diseases to adopt a new perspective on the role of FABP1, and endorse FABP1 as an important indicator of hyperuricemia." (PMID 36277716, 2022). "After further adjustment for age, BMI, sex, ALT, AST, and γ-GT levels in Model 3, there was no statistical difference in the association between FABP1 and the risk of hyperuricemia (OR, 95% CI = 1.022, 0.994–1.052, P = 0.125)." (PMID 36277716, 2022). "So we speculated that FABP1 and hyperuricemia may interact through liver function-related indicators." (PMID 36277716, 2022). "In binomial logistic regression, ​we found that the association between serum FABP1 levels and the risk of hyperuricemia had no statistical effect after adjusting for liver enzymes." (PMID 36277716, 2022). "However, the relationship between FABP1 and hyperuricemia is unknown." (PMID 36277716, 2022). "However, the relationship between FABP1 and hyperuricemia remains unknown." (PMID 36277716, 2022). "FABP1 levels were higher but decreased more after LSG in obese patients with hyperuricemia than in those without hyperuricemia." (PMID 36277716, 2022). "However, hyperuricemia as a common metabolic disease is closely related to liver and pancreas islet function, and its relationship with FABP1 has not been reported." (PMID 36277716, 2022). "However, the link between FABP1 and hyperuricemia has not been reported." (PMID 36277716, 2022).
ischemic stroke (1 paper, 2023). A stroke disorder caused by obstruction of blood flow to the brain, due to thrombotic (local blood clot formation) or embolic (due to a blood clot or other material traveling from another site) event. "Association between different FABP1 genotype and risk factors for ischemic stroke." (PMID 37091779, 2023). "Here we evaluated the associations between alleles of FABP1 and FABP2 genes and ischemic stroke risk in 251 Chinese Han patients." (PMID 37091779, 2023). "The present study aimed to determine the association between FABP1 or FABP2 and ischemic stroke." (PMID 37091779, 2023).
medullary carcinomas (1 paper, 2025). "FABP1 is significantly downregulated in MSI (microsatellite instable) and medullary carcinomas, and its loss is associated with right-sided tumour location, high grade, and increased tumour-infiltrating lymphocytes." (PMID 41149452, 2025).
peritoneal disease (1 paper, 2022). "In addition to the presence of peritoneal disease, by the transcriptome analysis of paired samples of neoplastic tissue and normal gastric mucosa, we have identified a group of six differentially expressed genes that predict poor prognosis: ONG, FABP1, LIF, ONECUT2, SFRP2, and GPA33." (PMID 35847866, 2022).
phospholipidosis (1 paper, 2024). "Additionally, the downregulation of FABP1, HPN, and SERPINA3 genes is related to phospholipidosis." (PMID 38992651, 2024).
pulmonary hypertension (1 paper, 2021). Increased pressure within the pulmonary circulation due to lung or heart disorder. "Interestingly, FABP1 levels were associated with markers of congestion and alteration of parameters for systolic and diastolic reserve, biventricular filling pressures, pulmonary hypertension, and CO during exercise in HFpEF." (PMID 34707207, 2021).